TBCEL-TECTA (TBCEL-TECTA readthrough)
Gene: Protein-coding gene on chromosome 11 (121,024,125 to 121,113,108, forward strand). Ensembl gene ENSG00000285509.
Genetic constraint (gnomAD): Loss-of-function variants: 22 observed, 54.42 expected, observed/expected ratio (o/e) 0.4, 90% interval 0.29 to 0.58. The upper end of that interval is the gene's LOEUF score, 0.58, which puts it in group 2 of 6, group 1 being the genes least tolerant of losing a copy. Missense variants: 391 observed, 597.44 expected, observed/expected ratio (o/e) 0.65, 90% interval 0.6 to 0.71. Synonymous variants: 188 observed, 224.61 expected, observed/expected ratio (o/e) 0.84, 90% interval 0.74 to 0.94.
Diseases named in the same sentence as TBCEL-TECTA in open-access papers:
TBCEL-TECTA is named in the same sentence as 1 disease in open-access papers, as found by Europe PMC text mining. Sharing a sentence is not in itself a finding about the gene and the disease. The quoted sentences say what the papers report.
tumour (1 paper, 2025). "Other targets included Filaggrin-2, peroxiredoxin 6, Calmodulin-like protein 5, TBCEL-TECTA readthrough protein, Desmocollin 1 and 3, and Desmoplakin variant protein—with implications in diagnosis and tumour progression." (PMID 40725142, 2025).